GLP1R (glucagon like peptide 1 receptor)
Diseases named in the same sentence as GLP1R in open-access papers (continued):
Sharing a sentence is not in itself a finding about the gene and the disease.
insulinomas (continued). "Exendin-4, which targets the glucagon-like-peptide 1 receptor (GLP-1R) overexpressed in insulinomas and in congenital hyperinsulinism, is an example thereof." (PMID 37665477, 2023). "Exendin-4 is a molecular tracer targeting GLP-1R; thus, it has high sensitivity and specificity in the diagnosis of insulinoma." (PMID 37455905, 2023). "We examined the renal retention and insulinoma targetingproperties of these new exendin analogues in a nude mouse model bearingsubcutaneous GLP-1R-expressing insulinomas." (PMID 37265006, 2023). "The renalretention and insulinoma targeting properties of these new exendinanalogues labeled with 68Ga or 177Lu have beenevaluated in a xenograft mouse model bearing subcutaneous GLP-1R-expressinginsulinomas." (PMID 37265006, 2023). "Other more common tracers such as 18F-fluorodopa (18F-DOPA) have shown some application on insulinoma imaging, although very few data are available and, at first glimpse, they are less promising than GLP1-R imaging." (PMID 37109517, 2023). "It has previously been shown that GLP-1R expression is more frequent in insulinomas than in other neuroendocrine tumours." (PMID 37894845, 2023). "Apart from diabetes, the GLP-1R is also an auspicious structural target for the detection of insulinomas and congenital hyperinsulinism (CHI), which are both conditions of hyper-insulin production resulting in hypoglycaemia." (PMID 37665477, 2023). "GLP-1R is the receptor with the highest expression level on the surface of insulinoma cells, which is about 6–12 times that of normal β cells, and GLP-1R is only expressed to a low degree or not expressed in other pancreatic tumors or non-tumor lesions." (PMID 37455905, 2023). "It was recognized that GLP-1R imaging originated from the study of insulinoma and afterwards was expanded in application including islet transplantation, pancreatic β-cell mass measurement, and ATP-dependent potassium channel-related endocrine diseases." (PMID 37780209, 2023). "Reubi and Waser utilised in vitro receptor autoradiography that identifies and quantifies peptide receptor proteins, and observed that over 90% of insulinomas (n = 27) showed an extremely high GLP-1R density." (PMID 37894845, 2023). "The overexpression of GLP-1Rs in insulinomas also shows high potential for tumour targeted therapy with radiolabelled GLP-1R-selective analogues." (PMID 37894845, 2023). "A high density of the glucagon-like peptide 1 receptor (GLP-1R) expression was identified on frozen insulinoma biopsy specimens, indicating GLP-1R as a potential target for radiotheranostics." (PMID 37242457, 2023). "The synthesized molecular compound that used exendin-4 as a substrate also demonstrated an ideal tumor background ratio and insulinoma sensitivity, making it an ideal choice for GLP-1R molecular imaging." (PMID 37780209, 2023). "Such promising results are encouraging, and it indicates that GLP1-R molecular imaging is gradually replacing conventional imaging as the non-invasive modality of choice for the accurate preoperative localization of insulinoma." (PMID 37780209, 2023). "Overexpression of this receptor has been demonstrated in benign insulinomas, establishing new GLP-1R target imaging in these tumors." (PMID 37109517, 2023). "An example thereof is Ex-4, an incretin mimetic drug that binds to the GLP-1R overexpressed on insulinomas and in hyperinsulinism." (PMID 37665477, 2023). "The perspectives of PRRT of insulinomas with a radiolabeled agonist remain remote today due to high kidney uptake and adverse effects elicited by GLP-1R activation." (PMID 37242457, 2023). "In tumour models of pancreatic insulinomas expressing the GLP-1R, Ex4 radiolabelled with the γ-emitter indium-111 accumulated with 287% iA/g in the tumour at 4 h p.i.." (PMID 37665477, 2023).
insulinomas (continued). "As the study was conducted in a tumor model with non-physiological GLP-1R expression, the efficacy of the treatment needs to be confirmed in a model with GLP-1R expression comparable to human insulinomas." (PMID 37242457, 2023). "The failure of the investigations above based on 177Lu-labeled exendin-4 to complete GLP-1R molecular imaging and targeted therapy in insulinoma models will present an emerging opportunity for our long-term research." (PMID 37780209, 2023). "This article provides an overview of the current status of GLP-1R molecular imaging in insulinoma, endocrinology and other related fields." (PMID 37780209, 2023). "Although exendin-4, the most mature molecular probe for GLP-1R imaging, has been successful in insulinoma studies." (PMID 37780209, 2023). "GLP-1R molecular imaging is currently the most promising non-invasive method for detecting benign insulinoma and other GLP-1R-positive diseases." (PMID 37780209, 2023). "Nowadays, visualization of benign insulinomas with PET/CT by GLP-1R-directed radioligands is an established and high-sensitivity diagnostic technique." (PMID 37242457, 2023). "We have summarized the previous preclinical studies of GLP1-R molecular imaging in insulinoma and discovered that from 111In in the early days of exploration to the now mature 68Ga." (PMID 37780209, 2023). "GLP-1R is a G protein-coupled receptor that regulates insulin secretion and is an important target for diagnosis of insulinoma." (PMID 37455905, 2023). "To validate our model, namely INS-1 832/3 rat insulinoma cells, we first verified plasma membrane recruitment of β-arrestin 2 following GLP-1R stimulation." (PMID 37134170, 2023). "It acts as a double-edged sword, pushing GLP-1R forward while relying on it so that all current molecular imaging studies of insulinoma focus on exendin-4 and its derivatives." (PMID 37780209, 2023). "GLP-1R can also recruit, and induce signaling, via the Gαq and β-arrestin pathways and knockdown of β-arrestin-1 in rat insulinoma (INS1) cells decreases the ability of GLP-1 to promote GSIS." (PMID 35299971, 2022). "Another limitation of this radiopharmaceutical is the low GLP-1R expression reported in malignant insulinomas." (PMID 36431313, 2022). "On the contrary, emerging evidence supports the use of radiotracers binding Glucagon-like peptide-1 receptor (GLP-1R), a G-protein-coupled receptor expressed on pancreatic beta cells and overexpressed in insulinoma." (PMID 35325412, 2022). "Elevated kidney uptake in insulinoma patients remains a major limitation of radiometallated exendin-derived ligands of the glucagon-like peptide 1 receptor (GLP-1R)." (PMID 34432147, 2021). "In order to reach an improved tumor localization and enable targeted radiotherapy of malignant insulinomas as well as of other GLP-1R-overexpressing malignancies, further investigations on pharmacokinetically optimized peptides should be envisaged." (PMID 34432147, 2021). "This makes GLP-1R interesting for imaging of insulinomas, which are challenging to diagnose due to their small size and anatomical proximity to the kidneys." (PMID 34735669, 2021). "Expression of GLP-1R is limited in malignant insulinoma; however, they often express SSTR making them eligible for imaging with 68Ga-SSTR-PET." (PMID 34735669, 2021). "Targeting the glucagon-like peptide-1 receptor by exendin-4 has a high sensitivity in localizing insulinomas." (PMID 34735669, 2021). "Here, we demonstrated that the uptake of our PET tracer by the pancreatic insulinomas is colocalized with insulin-secreting cells expressing GLP-1R." (PMID 31903128, 2020). "GLP-1R agonists are particularly useful for benign insulinoma detection, but their accuracy decreases in the case of malignant insulinomas." (PMID 33297381, 2020). "The co-registration of a low dose CT with GLP-1R SPECT of PET images usually helps to differentiate between an insulinoma and Brunner’s glands." (PMID 31951592, 2020).
insulinomas (continued). "Other nuclear medicine modalities are currently in development, such as glucagon-like peptide-1 receptor (GLP-1R) PET/CT for the diagnostic and localisation of insulinoma." (PMID 32947997, 2020). "The latest agents being used for the detection of insulinomas are glucagon-like peptide-1 receptor (GLP-1R) agonists, which have been proven to have a high sensitivity compared to SSTR2 analogs." (PMID 33297381, 2020). "rtPDT with exendin-4-IRDye700DX caused significant phototoxicity in cells with high GLP-1R expression (CHL-GLP-1R cells) and in the rat insulinoma cell line (INS-1 cells), with GLP-1R expression comparable to that in human insulinomas." (PMID 32385165, 2020). "Broader deployment of exendin-4 mediated GLP-1R PET scanning in the clinic for theranostic studies (outside of insulinoma management) is based on the availability of some crucial data." (PMID 31903131, 2020). "In both patients the GLP-1R positive lesion was surgically resected, and histologic analysis confirmed the insulinoma." (PMID 31951592, 2020). "GLP-1R imaging using 111In- and 68Ga-labeled exendin-4 has been shown to be a successful preoperative imaging technique for insulinomas and is also under investigation in CHI (NCT03768518; clinicaltrials.gov)." (PMID 32385165, 2020). "In contrast to benign insulinomas, malignant insulin-secreting neuroendocrine tumors express GLP-1R in only one-third of the cases, while they more often express the somatostatin subtype 2 receptors." (PMID 31951592, 2020). "GLP-1R agonists, such as exendin-4, are particularly useful for benign insulinoma detection, but their accuracy decreases in the case of malignant insulinomas." (PMID 33297381, 2020). "On the other hand GLP-1R PET/CT with 68Ga-NODAGA-exendin-4 detected insulinomas with a much higher sensitivity than SSTR PET/CT (93.5 vs 61.3%) in a prospective comparison in 31 patients with biochemically proven hyperinsulinemic hypoglycemia." (PMID 31951592, 2020). "The tracer was tested in nude mice bearing subcutaneous INS-1 insulinoma tumors with GLP-1R and MDA-MB-435 tumors of melanoma origin with low GLP-1R expression." (PMID 31903131, 2020). "We showed that the uptake of radiolabeled Ex4 was higher in the entire pancreas of RIP1-Tag2 mice developing overtime pancreatic insulinomas by hyperplasia of β-cells expressing GLP-1R." (PMID 31903128, 2020). "Targeting GLP-1R with indium-111, technetium-99m or gallium-68-labeled exendin-4 offers a new approach that permits the successful localization of small benign insulinomas." (PMID 31951592, 2020). "Radiolabeled exendin-4 (Ex4) derivatives are used to target the glucagon-like peptide-1 receptor (GLP-1R) for the clinical diagnosis of insulinomas, a rare type of neuroendocrine tumor." (PMID 31659487, 2019). "A study showed that only 36% of malignant insulinomas express GLP-1R, resulting in a low detection rate of malignant insulinoma by GLP-1R imaging." (PMID 31743337, 2019). "Steady-state Exendin-9 concentrations were ∼0.4 μg/mL (∼120 nmol/L), ∼2-fold above the binding affinity of Exendin-9 for GLP1R in human insulinoma cells." (PMID 30726726, 2019). "It has been reported that nonesterified fatty acid (NEFA) treatment decreased GLP-1 receptor (GLP-1R) expression in rodent insulinoma cell lines and isolated islet and led to impaired GLP-1 signaling." (PMID 31485457, 2019). "Because there is high expression of GLP-1R in insulinomas, its binding to the GLP-1RA probe labeled by different radionuclides can identify the tumor location." (PMID 31743337, 2019). "Insulinomas generally express highly and specifically the glucagon-like peptide-1 receptor (GLP-1R) as they are of β-cell origin." (PMID 31659487, 2019). "Benign insulinomas usually express glucagon-like peptide-1 receptors (GLP-1R), and imaging with different radiolabelled-exendin-4 compounds (i.e., 68Ga-NOTA-exendin-4) is recommended, with a sensitivity up to 90%." (PMID 30140282, 2018).
insulinomas (continued). "In this study, we evaluated an exendin-4 analogue, modified with a silicon containing building block, in order to elucidate its potential as an imaging agent for targeting GLP-1R positive insulinoma." (PMID 29503858, 2018). "The glucagon-like peptide type 1 receptor (GLP-1R) is overexpressed in virtually all benign insulinoma with high incidence and density and is considered a valuable target for the efficient visualisation by radiotracers." (PMID 29503858, 2018). "Analogues of exendin-4 have been radiolabeled for imaging the glucagon-like peptide type 1 receptors (GLP-1R) which are overexpressed in insulinoma." (PMID 29503858, 2018). "Herein we report on the radiosynthesis, in vitro and in vivo evaluation of a 18F–silicon-based exendin-4 derivative as a probe for imaging GLP-1R positive insulinoma." (PMID 29503858, 2018). "The sstr density is low in benign insulinomas even though they are neuroendocrine tumors, whereas GLP-1R is expressed with high incidence and density." (PMID 28295000, 2017). "Exendin-4 analogs that are relatively stable agonists of GLP-1R labeled with γ emitting radionuclides such as 111In and 99mTc demonstrated high sensitivity in GLP-1R imaging and insulinoma detection with SPECT." (PMID 28295000, 2017). "Glucagon-like peptide-1 receptor (GLP-1R) imaging using 111In-exendin-4 SPECT/CT has been shown to be more sensitive in detection of insulinoma than CT or MRI." (PMID 26034506, 2015). "With the help of precise preoperative localization of insulinoma with GLP-1R imaging the surgeon is able to minimize the amount of resected healthy pancreatic tissue." (PMID 26034506, 2015). "In contrast GLP-1R imaging using 111In-DOTA-exendin-4 SPECT/CT detected an insulinoma in the pancreatic corpus." (PMID 26034506, 2015). "Based on these three cases and the previously published data we recommend preoperative GLP-1R imaging in insulinoma patients." (PMID 26034506, 2015). "In our experience the preoperative GLP-1R imaging leads to focused access to the insulinoma, preservation of more normal pancreatic tissue and thus to a higher precision and safety of the procedure." (PMID 26034506, 2015). "Radiolabelled derivatives of exendin-4, a ligand for GLP-1R, have been successfully used to image insulinoma in patients." (PMID 25006548, 2014). "Among all GLP-1R expressing tumor types, insulinomas are at present of highest clinical interest for an in vivo targeting in patients, based on several considerations." (PMID 23230431, 2012). "Contrary to benign insulinomas, malignant insulinomas more often express sst2 receptors than GLP-1R." (PMID 23230431, 2012). "A more extensive study with data from 10 patients with malignant insulinoma showed that somatostatin receptors type 2 were expressed in seven patients, whereas GLP-1R were present in four patients, and both receptors in only one patient." (PMID 23230431, 2012). "The same Rip1tag2 mouse model also provided preliminary data on GLP-1R-targeted therapy of insulinoma." (PMID 23230431, 2012). "First, insulinomas exhibit particularly high GLP-1R expression levels with respect to both incidence and density." (PMID 23230431, 2012). "Of practical importance, with the exception of Brunner’s glands, the different tissues in the pancreatic area (i.e., pancreas islets and acini, intestines, and kidney) exhibit far lower GLP-1R density levels than insulinomas." (PMID 23230431, 2012). "Initially, GLP-1R targeting was performed in the rat insulinoma cell line RINm5F and in a rat insulinoma animal model (NEDH rats) using 125I-labeled GLP-1 and exendin-3." (PMID 23230431, 2012). "Targeting GLP-1R with 111In-DOTA-exendin-4 or 111In-DPTA-exendin-4 offers a new approach that permits the successful localization of small benign insulinomas pre- and intraoperatively." (PMID 23230431, 2012).
insulinomas (continued). "Malignant insulinomas, in contrast to their benign counterparts, express GLP-1R in only one-third of the cases, while they more often express the somatostatin type 2 receptors." (PMID 23230431, 2012). "Thus, positron emission tomography (PET) targeting the glucagon-like peptide 1 receptor (GLP-1R) has evolved as a noninvasive specific tool for the diagnosis of insulinoma." (PMID 40405975, 2025). "In contrast, aggressive insulinomas preferentially express somatostatin receptor subtype 2 (SSTR2) instead of GLP-1R, and, in such cases, SSTR-SPECT scans may be utilized." (PMID 40648766, 2025). "In that regard, insulinomas have been reported to express GLP-1R." (PMID 41312422, 2025). "Glucagon-like peptide-1 receptors (GLP-1R) are overexpressed in 93% of localized insulinomas." (PMID 38893191, 2024). "Our main findings were that non-metastatic insulinomas express GLP-1R and the lack of GLP-1R expression is associated with metastatic disease and impaired overall survival in patients with sporadic insulinomas." (PMID 37894845, 2023). "In conclusion, the lack of GLP-1R expression is associated with metastatic disease and impaired survival in insulinoma patients." (PMID 37894845, 2023). "Previous studies have found that the sensitivity of 68Ga-Exendin-4 positron emission tomography/computed tomography (PET/CT) targeting glucagon-like peptide-1 receptor (GLP-1R) to localize insulinoma could reach 97.7%." (PMID 37455905, 2023). "This section summarizes the previous 21 years of GLP-1R molecular imaging in insulinoma." (PMID 37780209, 2023). "Summary of clinical studies of GLP-1R molecular imaging in insulinoma." (PMID 37780209, 2023). "Recent findings suggest that GLP-1R-targeted radionuclide therapy with 111In-labeled exendin-4 derivatives could be useful in the future treatment of selected patients with an insulinoma." (PMID 37894845, 2023). "Therefore it becomes the biggest obstacle to advancing GLP-1R molecular medicine treatment in insulinoma." (PMID 37780209, 2023). "Also, when insulinoma cells are treated with liraglutide, a glucagon-like peptide-1 receptor agonist, an increase in the autophagy rate is observed." (PMID 37759604, 2023). "GLP-1R molecular imaging has become a potential direction for diagnosing insulinoma in MEN-1." (PMID 37780209, 2023). "The lack of GLP-1R expression was associated with a significantly impaired overall survival in patients with sporadic insulinomas." (PMID 37894845, 2023). "Hence, these factors have directly or indirectly hindered the exploration of GLP-1R molecular imaging in tumor diseases other than insulinoma." (PMID 37780209, 2023). "A promising clinicalimaging strategy to visualize (benign) insulinomas and native betacells in the pancreas is based on glucagon-like peptide-1 receptor(GLP-1R) targeting using radiolabeled exendin and SPECT/CT or PET/CT.3−5 The GLP-1R is highly and specifically expressed on beta cells." (PMID 37265006, 2023). "Furthermore, the success of clinical translation more or less determines the future of molecular imaging of GLP-1R in insulinoma." (PMID 37780209, 2023). "Summary of preclinical studies of GLP-1R molecular imaging in insulinoma." (PMID 37780209, 2023). "Pre-operative GLP-1R imaging with radiolabeledexendin can be used to accurately localize insulinoma lesions; however,some tumors may be missed because they are masked by the high kidneyuptake." (PMID 37265006, 2023). "In fact, concerning functioning NENs, different radiotracers have been shown to increase sensitivity and specificity in different clinical syndromes, such as ectopic ACTH syndromes or insulinomas, due to their expression of glucagon-like peptide 1 receptor (GLP1R)." (PMID 35626118, 2022). "Interestingly, GLP-1R has been utilized to mediate tumor specificity for insulinoma that highly expresses GLP-1R during radiotherapy." (PMID 36569936, 2022).